UBIAD1 (UbiA prenyltransferase domain containing 1)
Diseases named in the same sentence as UBIAD1 in open-access papers (continued):
Sharing a sentence is not in itself a finding about the gene and the disease.
melanoma (continued). "We thus examined the subcellular localization of UBIAD1 in melanoma cell lines SkMel28 and A375 and in normal melanocytes HEMa-LP." (PMID 35255427, 2022). "We show that UBIAD1 and plasma membrane CoQ10 sustain melanoma cell survival and proliferation by preventing lipid peroxidation and cell death." (PMID 35255427, 2022). "This view is supported by our findings that UBIAD1/CoQ10/NQO1 axis disruption is sufficient to trigger cell death in melanoma cell lines despite the presence of other antioxidant enzymes." (PMID 35255427, 2022). "We selected some BRAF- and NRAS-mutated cell lines such as SkMel28, A375 and Mel Juso to study the role of UBIAD1 in the antioxidant defense of melanoma." (PMID 35255427, 2022). "Next, we investigated UBIAD1 expression across multiple human melanoma cell lines both at protein and mRNA levels." (PMID 35255427, 2022). "Altogether, these data demonstrate that UBIAD1 is required to sustain survival and that it exerts this effect through the synthesis of CoQ10 in melanoma cells." (PMID 35255427, 2022). "To understand the function of UBIAD1 in melanoma, we focused our studies on SkMel28 and A375 cell lines, carrying the BRAFV600E-mutation, and the Mel Juso cell line, carrying the NRASQ61L-mutation." (PMID 35255427, 2022). "Immunofluorescence data showed that UBIAD1 is mainly co-localized to the Golgi in melanoma cell lines compared to healthy melanocytes where it is mainly present in ER." (PMID 35255427, 2022). "UBIAD1 mRNA levels fluctuate among melanoma cells with the MM165, A375 and SkMel28 showing the highest levels." (PMID 35255427, 2022). "Therefore, H-Ras and UBIAD1 may be associated with melanoma formation." (PMID 30518913, 2018). "•Melanoma cell lines are dependent on UBIAD1 and plasma membrane CoQ10 for cell survival." (PMID 35255427, 2022). "Additionally, we show that the NAD(P)H Quinone Dehydrogenase 1 (NQO1), responsible for the 2-electron reduction of CoQ10 on plasma membranes, acts downstream of UBIAD1 to support melanoma survival." (PMID 35255427, 2022). "Thus, to better characterize the mechanism involved in UBIAD1-mediated survival of melanoma cells, we analyzed ROS levels in UBIAD1KD cells." (PMID 35255427, 2022). "Furthermore, UBIAD1 and CoQ10 levels are upregulated in melanoma cells with respect to melanocytes." (PMID 35255427, 2022). "Last, we evaluated the changes in mRNA expression of UBIAD1, NQO1 and FSP1 upon UBIAD1KD or NQO1KD in melanoma cells." (PMID 35255427, 2022). "For this purpose, we carefully titered UBIAD1 and NQO1 knockdown in SkMel28 and A375 melanoma cell lines at suboptimal level (UBIAD1KD Low and NQO1KD Low) to avoid complete cell death as for UBIAD1KD and NQO1KD." (PMID 35255427, 2022). "We found that idebenone treatment in UBIAD1KD cells can significantly restore expression of these markers in all melanoma cell lines tested (except for RRM2 in Mel Juso), supporting the functional role of CoQ10 in UBIAD1-dependent melanoma survival." (PMID 35255427, 2022). "The effect of UBIAD1/CoQ10 and NQO1 in survival of melanoma cell lines in vitro suggests to further consider these two enzymes as new therapeutic targets in melanoma research." (PMID 35255427, 2022). "To demonstrate the existence of a UBIAD1/CoQ10/NQO1 axis that regulates and maintains cell survival in ROS-dependent melanoma cell lines, we sought to understand whether the two enzymes could have a synergistic effect." (PMID 35255427, 2022). "•UBIAD1 and COQ10 protect melanoma cells from lipid peroxidation and apoptotic cell death." (PMID 35255427, 2022). "We envision UBIAD1 and NQO1 blockade as novel therapeutic strategies in melanoma." (PMID 35255427, 2022). "In particular, it could be interesting to study UBIAD1/CoQ10/NQO1 axis in those situations where oxidative stress drives resistance to therapy (e.g. BRAF and MEK inhibitors-resistant melanoma)." (PMID 35255427, 2022).
melanoma (continued). "Also, the role of UBIAD1 in synthesis of non-mitochondrial CoQ10 was beneficial for the melanoma cells since it prevented lipid peroxidation and cell death." (PMID 36275615, 2022). "By immunofluorescence we showed that UBIAD1 is co-localized mainly to Golgi and to a lesser extent to ER in melanoma cells with respect to melanocytes, consistently with previous data suggesting that the biosynthesis of non-mitochondrial CoQ10 by UBIAD1 is localized to Golgi." (PMID 35255427, 2022). "However, it still remains to be further explored the functional cross-talk between UBIAD1 and NQO1 in melanoma progression and whether the blocking of these enzymes would represent a valid therapeutic approach to treat melanoma." (PMID 35255427, 2022). "However, the concomitant mild silencing of both UBIAD1 and NQO1 enzymes had a dramatic effect on cell survival (UBIAD1KD Low + NQO1KD Low), suggesting a synergistic effect of the two enzymes in protecting melanoma cells from cell death." (PMID 35255427, 2022). "Whether UBIAD1 is involved in melanoma progression has not been addressed, yet." (PMID 35255427, 2022). "While it was reported that UBIAD1 is responsible for the biosynthesis of vitamin K2, we did not detect vitamin K2 in melanoma cells by HPLC measurement (data not shown), confirming that UBIAD1 is not required for generating Vitamin K2 in melanoma cells." (PMID 35255427, 2022).
breast carcinoma (2 papers, 2019 to 2023). "The significant findings included associations between self-reported history of breast cancer and hypomethylation within cg06072257 and cg06123699, which are located near UBIAD1 and TPRG1 on chromosomes 1 and 3, respectively (p = 6.5 × 10−103 and p = 2.4 × 10−101, respectively)." (PMID 37410739, 2023). "The novel associations observed in this study could strengthen evidence for candidate molecular pathways underlying peripheral disease states, e.g., self-reported history of breast cancer associated with differential methylation at cg06072257 (UBIAD1) and cg06123699 (TPRG1)." (PMID 37410739, 2023). "Further studies to evaluate the function of UBIAD1 in relation to cellular K1 and K2 content and GGCX activity in breast cancer cells are ongoing to test this model." (PMID 31040920, 2019).
metastatic prostate carcinoma (2 papers, 2013 to 2014). A carcinoma that arises from the prostate gland and has spread to other anatomic sites. "UBIAD1 (also known as TERE1) message and protein expression is reduced in human bladder transitional cell carcinoma (TCC) and metastatic prostate cancer." (PMID 25127365, 2014).
prostate tumor (2 papers, 2013 to 2015). "UBIAD1 (also known as TERE1) was first described as being absent or markedly diminished in bladder and prostate tumors and belongs to the UbiA superfamily of prenyltransferases." (PMID 25742604, 2015).
renal carcinoma (2 papers, 2016 to 2019). A carcinoma arising from the epithelium of the renal parenchyma or the renal pelvis. "In HEK293 cells and bladder, prostate and renal cancer cells, elevated UBIAD1 expression reduced cholesterol levels." (PMID 26890002, 2016).
acute pancreatitis (1 paper, 2019). An acute inflammatory process that leads to necrosis of the pancreatic parenchyma. "The pathology of the UBIAD1-deficient pancreas is similar to that of acute pancreatitis, resulting in the disappearance of pancreatic acinar cells, which are replaced by adipocytes." (PMID 31013667, 2019).
Cerebral ischemia (1 paper, 2021). Restriction of arterial blood supply to the brain associated with insufficient oxygenation to support the metabolic requirements of the tissue. "In the previous study, we demonstrated that the expression of UBIAD1 decreased under the condition of ischemic stroke, and over-expression of UBIAD1 significantly protects against cerebral ischemia/reperfusion-induced neuronal apoptosis." (PMID 34104092, 2021). "Up-regulating the expression of UBIAD1 could attenuated cerebral ischemia/reperfusion-induced mitochondrial fragmentation and dysfunction 38, and ameliorated the fragmentation and reduced the level of oxidative stress-related protein expression in both the endoplasmic reticulum and Golgi apparatus." (PMID 34104092, 2021).
chronic kidney disease (1 paper, 2024). Impairment of the renal function secondary to chronic kidney damage persisting for three or more months. "For example, during the development of rat chronic kidney disease (CKD), renal MK-4 levels rose, but UBIAD1 and VKORC1 expression decreased." (PMID 39057059, 2024).
chronic pancreatitis (1 paper, 2019). A chronic inflammatory process causing damage and fibrosis of the pancreatic parenchyma. "The pathology of the pancreas in tamoxifen-treated UBIAD1-cKO mice is similar to that of chronic pancreatitis." (PMID 31013667, 2019).
glioma (1 paper, 2022). A benign or malignant brain and spinal cord tumor that arises from glial cells (astrocytes, oligodendrocytes, ependymal cells). "Down-regulation of UBIAD1 has been shown to activate Ras-MAPK signaling, one of the main signaling networks in gliomas." (PMID 35158753, 2022).
hematoma (1 paper, 2021). A hematoma is a collection of blood from a vascular structure into an extravascular space. "Compared with the sham group, the expression of UBIAD1 in peri-hematoma tissue decreased at 6 hours after ICH insult, reached the lowest at 72 hours, and then increased." (PMID 34104092, 2021).
Hypercholesterolemia (1 paper, 2011). An increased concentration of cholesterol in the blood. "The fact that UBIAD1 likely plays a role in cholesterol biochemistry indicates that the association with hypercholesterolemia is real." (PMID 21572737, 2011).
ischemic stroke (1 paper, 2021). A stroke disorder caused by obstruction of blood flow to the brain, due to thrombotic (local blood clot formation) or embolic (due to a blood clot or other material traveling from another site) event. "Previously, we discussed the expression and role of UBIAD1 in an ischemic stroke model, and it has been confirmed that UBIAD1 overexpression has an obvious protective effect on OGD/R-induced cells in vitro model." (PMID 34104092, 2021).
lung adenocarcinoma (1 paper, 2015). A carcinoma that arises from the lung and is characterized by the presence of malignant glandular epithelial cells. "The effectors of module 3 – DNA methylations of UBIAD1 and VAV1 – are less well-known in lung adenocarcinoma." (PMID 26160836, 2015).
lymphoma (1 paper, 2017). A malignant (clonal) proliferation of B- lymphocytes or T- lymphocytes which involves the lymph nodes, bone marrow and/or extranodal sites. "This study is the first to apply VK2 in the treatment of UBIAD1/heix mutation-induced Drosophila Lymphoma LiD." (PMID 29213118, 2017). "However, its effect on lymphoma induced by UBIAD1/heix mutation in Drosophila remains unknown." (PMID 29213118, 2017).
pancreatitis (1 paper, 2019). Inflammation of the pancreas. "Although the functions of UBIAD1 and MK-4 in the pancreas are not clear, periostin, a member of a vitamin K-dependent γ-carboxylated protein family, is reported to be involved in pancreatitis." (PMID 31013667, 2019).
Stillbirth (1 paper, 2014). Death of the fetus in utero after at least 22 weeks of gestation. "A weanling Ubiad1−/− mouse on day 1 from the Ubiad1+/− mice orally administered CoQ10 throughout pregnancy died immediately after birth or stillbirth." (PMID 25127365, 2014).
tumor (16 papers, 2012 to 2025). "These PPIs can be referred cancer-related molecular events under conditions of HSP90 and UBIAD1 overexpression which is associated with tumor progression, up-regulation of the mevalonate pathway and cholesterol accumulation." (PMID 34440098, 2021). "Our study suggests that UBIAD1 serves as a tumor suppressor in cancer and tentatively reveals the underlying mechanism of melanotic mass formation in Drosophila." (PMID 30518913, 2018). "Exosomal miR-4644, upregulated in the plasma of BC patients, enhances tumor growth by downregulating UBIAD1, a gene involved in tumor suppression." (PMID 40693234, 2025). "A previous report also demonstrated that the UBIAD1 protein is a tumor suppressor based upon its reduced expression in urological cancer specimens." (PMID 37670241, 2023). "Recent research on this tumor suppressor show that UBIAD1 protects the cholesterol biosynthetic enzyme HMG-CoA reductase from degradation and plays an important role in vascular cell calcification." (PMID 30518913, 2018). "Based upon flow cytometry analysis, it is shown that mutation of the RPWS motif reduced the UBIAD1-induced apoptosis of T24 cells, indicating that the proper Golgi localization of UBIAD1 influences its tumor suppressant activity." (PMID 23977195, 2013). "Disrupting the Golgi localization of UBIAD1 affects its tumor suppressing activity, suggesting that Golgi localization of UBIAD1 influences its biological function as a tumor suppressor." (PMID 23977195, 2013). "A novel Golgi retention signal, RPWS, was identified, which affects the tumor suppressing activity of UBIAD1." (PMID 23977195, 2013). "In conclusion, disrupting the Golgi localization of UBIAD1 decreases the percentage of UBIAD1-induced late apoptosis cells, indicating that the tumor suppressing activity of UBIAD1 protein is at least partially influenced by its proper Golgi localization." (PMID 23977195, 2013). "Overall, our study paves the way for further understanding the molecular mechanism of UBIAD1, a tumor suppressor involved in the biosynthesis of vitamin K2 which is capable of inducing the apoptosis of cancer cells." (PMID 23977195, 2013). "The Golgi retention signal of UBIAD1 is a novel protein motif, RPWS, which influences the tumor suppressing activity of UBIAD1." (PMID 23977195, 2013). "To explore this connection, we tested the effect of removing the Golgi localization of UBIAD1 on its tumor suppressing activity." (PMID 23977195, 2013). "Furthermore, considering that UBIAD1 is downregulated in bladder and prostate carcinomas, and its overexpression inhibits tumor cell proliferation." (PMID 30518913, 2018). "In addition to its roles as a tumor suppressor and as a modulator for intracellular cholesterol, UBIAD1 has been shown to be the first enzyme responsible for human vitamin K biosynthesis." (PMID 23977195, 2013). "Thus, we hypothesize that in normal breast, K1 is converted to menadione which is prenylated by UBIAD1 to K2, favoring tumor suppression." (PMID 31040920, 2019). "The fact that disruption of the Golgi localization of UBIAD1 only partially affects its tumor suppressing activity implies that the subcellular localization of UBIAD1 on other intracellular organelles such as ER or mitochondria may also contribute to its tumor suppressing activity." (PMID 23977195, 2013). "ScRNA‐seq data show that vitamin K cycle genes(NQO1, UBIAD1, GGCX, VKORC1, VKORC1L1) are specifically expressed in tumor cells." (PMID 41028931, 2025). "The authors hypothesized that in normal breast, VK1 is converted to VK3, which is then prenylated by the enzyme UbiA prenyltransferase domain containing 1 (UBIAD1) to VK2, favoring tumor suppression." (PMID 33917442, 2021).
cancer (13 papers, 2007 to 2023). A tumor composed of atypical neoplastic, often pleomorphic cells that invade other tissues. "Downregulation of UbiA prenyltransferase domain-containing protein 1 (UBIAD1), also known as transitional epithelial response protein 1 (TERE1), is a hallmark of a majority of cancers." (PMID 33204397, 2020). "However, down-regulation of UBIAD1 is a hallmark of multiple cancers, according to the Human Protein Atlas, and this prenyltransferase is one of the newest prognostic markers discussed in cancer, according to recent cohort studies." (PMID 35158753, 2022). "Recent cohort studies highlight UBIAD1 expression and activity as one of the newest prognostic markers in cancer." (PMID 37176145, 2023). "The conversion of menadione to vitamin K2 should be suppressed in cancer cells due to down-regulation of UBIAD1." (PMID 35158753, 2022). "Changes to this consensus sequence can lead to cholesterol dysregulation, and it has been shown that ectopic UBIAD1 expression or induction of endogenous UBIAD1 in human cancer cell lines can reduce elevated cholesterol levels." (PMID 27382485, 2016). "The role of the UBIAD1 metabolic enzyme in cancer progression has been poorly investigated." (PMID 35255427, 2022). "It is speculated that the UBIAD1 product, MK-4, has a beneficial role in the protection of diverse types of cancer, however an in-depth investigation is needed in these areas." (PMID 36275615, 2022). "This is indirect evidence that UBIAD1 could be a key factor in the selective cytotoxicity of M/A to cancer cells, and this is the subject of ongoing study in our team." (PMID 35158753, 2022). "Clearly a directed study of intracellular cholesterol transport in the relevant cancers may clarify the role of TERE1/UBIAD1." (PMID 17668063, 2007). "It is highly controversial whether UBIAD1 plays a role in anti-cancer effect or cancer progression." (PMID 36275615, 2022). "Moreover, vitamin C/menadione could achieve a selective cytotoxicity against cancer cells due to the rapid UBIAD1-mediated conversion of menadione to vitamin K2 in normal cells and downregulation of UBIAD1 in the majority of cancers leading to strong inhibition of this conversion." (PMID 32411317, 2020). "UBIAD1 is also involved in the regulation of cholesterol levels via steroid and xenobiotic receptor (SXR) target genes, as well as the synthesis of ubiquinones —decisive factors in inducing carcinogenesis and survival of cancer cells." (PMID 35158753, 2022). "We assume that the ability of normal cells to convert menadione to vitamin K2 (which has a membrane binding tail) is diminished or absent for cancer cells due to the downregulation of UBIAD1 (TERE1)." (PMID 33204397, 2020). "Ras translocates to the plasma membrane in the absence of UBIAD1, leading to the formation of cancer." (PMID 30518913, 2018).
autosomal dominant disease (2 papers, 2014 to 2018). Autosomal dominant form of disease. "In human studies, UBIAD1 has been implicated in SCD, a rare autosomal-dominant disease associated with at least one of 22 different heterozygous UBIAD1 missense mutations." (PMID 25127365, 2014).
cardiovascular disease (2 papers, 2007 to 2013). "Recently, UBIAD1 has been shown to be a CoQ10 synthase localized in the Golgi membranes associated with cardiovascular disease." (PMID 23977195, 2013). "It is intriguing to speculate that UBIAD1 may play a role in cardiovascular disease, or may be a potential novel target for modulation of circulating or intracellular HDL cholesterol levels." (PMID 17668063, 2007).
genetic disease (2 papers, 2014 to 2015). "For example, the missense mutation of UBIAD1 responsible for the human genetic disorder SCD was used to investigate changes in enzyme activities and enabled the identification of a key structural site for the MK-4 synthetic activity of UBIAD1." (PMID 25874989, 2015).
myopathy (1 paper, 2020). A disease of the muscle in which the muscle fibers do not function properly. "Support for this possibility requires MK-4 rescue experiments in Ubiad1-deficient mice and determination of whether HmgcrKi/Ki mice with skeletal muscle-specific knockout of Ubiad1 develop myopathy." (PMID 32118581, 2020). "The observation that Ubiad1-/-: :HmgcrKi/Ki mice exhibit signs of muscle injury suggests statin-induced myopathy may in part, result from MK-4 depletion." (PMID 32118581, 2020).